LINC01878 (long independently transcribed non-coding RNA 1878)
Gene: Long non-coding RNA gene on chromosome 2 (212,795,300 to 212,819,264, forward strand). Ensembl gene ENSG00000234308.
Diseases named in the same sentence as LINC01878 in open-access papers:
LINC01878 is named in the same sentence as 1 disease in open-access papers, as found by Europe PMC text mining. Sharing a sentence is not in itself a finding about the gene and the disease. The quoted sentences say what the papers report.
thyroid cancer (1 paper, 2021). "LINC01878 may play a vital role in thyroid cancer, which also had no experimental confirmation." (PMID 33869203, 2021).